MBTD1 (mbt domain containing 1)
Description:
Chromatin reader component of the NuA4 histone acetyltransferase complex, a multiprotein complex involved in transcriptional activation of select genes principally by acetylation of nucleosomal histones H4 and H2A. The NuA4 complex plays a direct role in repair of DNA double-strand breaks (DSBs) by promoting homologous recombination (HR). MBTD1 specifically recognizes and binds monomethylated and dimethylated 'Lys-20' on histone H4 (H4K20me1 and H4K20me2, respectively). In the NuA4 complex, MBTD1 promotes recruitment of the complex to H4K20me marks by competing with TP53BP1 for binding to H4K20me. Following recruitment to H4K20me at DNA breaks, the NuA4 complex catalyzes acetylation of 'Lys-15' on histone H2A (H2AK15), blocking the ubiquitination mark required for TP53BP1 localization at DNA breaks, thereby promoting homologous recombination (HR).
Synonyms: SA49P01; FLJ20055
Tractability: PROTAC: ubiquitination databases record sites on it; its protein half-life has been measured; a small molecule that binds it is known.
Target class: Methyl-lysine/arginine binding protein; MBT domain; Epigenetic regulator; Reader
Gene: Protein-coding gene on chromosome 17 (51,177,419 to 51,261,114, reverse strand). Ensembl gene ENSG00000011258.
Subcellular location: Nucleus; Chromosome
Subcellular location (Human Protein Atlas): Nucleoplasm; Cytosol
Gene Ontology:
Molecular function: histone H4K20me1 reader activity; histone H4K20me2 reader activity; NuA4 histone acetyltransferase complex binding; protein binding; chromatin binding; histone binding; zinc ion binding
Biological process: double-strand break repair via homologous recombination; positive regulation of double-strand break repair via homologous recombination; regulation of cell cycle; negative regulation of DNA-templated transcription; positive regulation of DNA-templated transcription; regulation of apoptotic process; regulation of double-strand break repair; chromatin organization; regulation of DNA-templated transcription
Cellular component: chromosome; NuA4 histone acetyltransferase complex; nucleoplasm; nucleosome; site of double-strand break; nucleus
Genetic constraint (gnomAD): Loss-of-function variants: 12 observed, 46.8 expected, observed/expected ratio (o/e) 0.26, 90% interval 0.16 to 0.41. The upper end of that interval is the gene's LOEUF score, 0.41, which puts it in group 1 of 6, group 1 being the genes least tolerant of losing a copy. Missense variants: 268 observed, 510.59 expected, observed/expected ratio (o/e) 0.52, 90% interval 0.47 to 0.58. Synonymous variants: 158 observed, 165.42 expected, observed/expected ratio (o/e) 0.96, 90% interval 0.84 to 1.09.
Homologues: Orthologues: chimpanzee MBTD1 (100% identical), macaque MBTD1 (99% identical), pig MBTD1 (99% identical), rabbit MBTD1 (99% identical), dog MBTD1 (99% identical), guinea pig MBTD1 (99% identical), mouse Mbtd1 (98% identical), rat Mbtd1 (97% identical), tropical clawed frog mbtd1 (88% identical), zebrafish mbtd1 (80% identical). Paralogues in human: L3MBTL2 (54% identical), SFMBT2 (17% identical), L3MBTL1 (16% identical), L3MBTL3 (16% identical), SCMH1 (16% identical), SCML2 (16% identical), L3MBTL4 (16% identical), SFMBT1 (16% identical), PHC1 (11% identical), PHC2 (10% identical), PHC3 (10% identical), SAMD11 (9% identical), and 6 more.
Diseases named in the same sentence as MBTD1 in open-access papers:
MBTD1 is named in the same sentence as 17 diseases in open-access papers, as found by Europe PMC text mining. Sharing a sentence is not in itself a finding about the gene and the disease. The quoted sentences say what the papers report.
osteosarcoma (7 papers, 2019 to 2023). A usually aggressive malignant bone-forming mesenchymal neoplasm, predominantly affecting adolescents and young adults. "In this paper, we found that the lncRNA TTN-AS1 and malignant brain tumour domain containing protein 1 (MBTD1) were overexpressed in osteosarcoma, and they were associated with the poor prognosis of osteosarcoma patients." (PMID 31600142, 2019). "MBTD1 was highly expressed in osteosarcoma and was associated with poor prognosis." (PMID 31600142, 2019). "For instance, miR-134-5p was downregulated in osteosarcoma, and the target gene MBTD1 was overexpressed, promoting cancer cell viability and inhibiting cell apoptosis." (PMID 38030848, 2023). "Perilous studies found that LncRNA TTN-AS1 regulates apoptosis and drug resistance in osteosarcoma cells through the miR-134-5p/MBTD1 axis." (PMID 35309947, 2022). "For instance, TTN-AS1 contributes to cell proliferation and drug resistance in osteosarcoma by targeting the miR-134-5p/mbt domain containing 1 (MBTD1) pathway." (PMID 34903127, 2021). "In conclusion, lncRNA TTN-AS1 promoted the expression of MBTD1 by targeting miR-134-5p and regulated cell growth, apoptosis and drug resistance in osteosarcoma." (PMID 31600142, 2019). "In this study, MBTD1 was highly expressed in osteosarcoma, and high levels of MBTD1 were closely related to malignancy and poor prognosis of osteosarcoma." (PMID 31600142, 2019). "Osteosarcoma patients with high expression of MBTD1 had worse 5-year survival rates compared to those with low expression of MBTD1 (50.005 vs. 26.43%)." (PMID 31600142, 2019). "However, further research is needed on the mechanisms by which TTN-AS1 participates in drug resistance and by which MBTD1 promotes the development of osteosarcoma." (PMID 31600142, 2019). "For example, in osteosarcoma, TTN-AS1 expression is markedly enhanced, and high TTN-AS1 expression is associated with the patients’ poor prognosis, and TTN-AS1 facilitates cancer cell multiplication and suppresses apoptosis via regulating the miR-134-5p/MBTD1 axis." (PMID 33517826, 2021). "In this study, we discovered the role of lncRNA TTN-AS1 and MBTD1 in osteosarcoma and analysed the mechanism by which lncRNA TTN-AS1 regulates apoptosis and drug resistance of osteosarcoma cells through the miR-134-5p targeting axis." (PMID 31600142, 2019). "However, the role of MBTD1 in osteosarcoma has not been studied." (PMID 31600142, 2019).
endometrial stromal sarcomas (5 papers, 2022 to 2025). "In endometrial stromal sarcoma, CXorf67 forms fusion genes with MBTD1, potentially disrupting polycomb group (PcG) functions." (PMID 42238311, 2025). "One such fusion identified in endometrial stromal sarcomas occurred between motifs 8–10 of EZHIP and MBTD1, a chromatin reader of the NuA4 histone acetyltransferase complex." (PMID 41427323, 2025). "The fusions reported in endometrial stromal sarcomas (ESS) include JAZF1-SUZ12, YWHAE-FAM22, ZC3H7-BCOR, MBTD1-CXorf67, and fusions of PHF1 with JAZF1, EPC1, and MEAF6." (PMID 35627126, 2022).
endometrial cancer (2 papers, 2019). Primary or metastatic malignant neoplasm involving the endometrium (mucous membrane that lines the endometrial cavity). "Importantly, the MBTD1-CXORF67 fusion protein contains the C-terminus of EZHIP and the highly conserved H3 K27M-like sequence, suggesting that PRC2 inhibition and loss of H3K27 methylation may support tumorigenesis of this subtype of endometrial cancer." (PMID 31086175, 2019).
bipolar disorder (1 paper, 2021). A disorder of the brain that causes unusual shifts in mood, energy, activity levels and the ability to carry out day-to-day tasks. "Also, only CEWAS found FAHD2B, HDAC5, MBTD1, NME2, and XPNPEP3 for bipolar disorder." (PMID 34807913, 2021).
malignant brain tumor (1 paper, 2025). "Mbt Domain Containing 1 (MBTD1), also known as Hemp (hematopoietic expressed mammalian polycomb) is a nuclear protein with a Cys2-Cys2 zinc finger domain and four malignant brain tumor (MBT) repeats." (PMID 41227365, 2025).
migraine (1 paper, 2022). "On comparing the migraine SCD group and SCD control group, one SNP, variant rs16949672 (in MBTD1 on chromosome 17), was identified." (PMID 35783123, 2022). "In contrast, this study showed that the MBTD1 gene protects patients from migraine under SCD conditions." (PMID 35783123, 2022). "In contrast, the SNP rs16949672 (in MBTD1) protects patients from migraine under SCD condition." (PMID 35783123, 2022).
oral cancers (1 paper, 2024). "This analysis revealed that in addition to the positive control GAPDH, all oral cancers upregulated the miR-145 downstream targets MBTD1 and FSCN1." (PMID 38396844, 2024). "In addition, several downstream targets of these specific microRNAs were upregulated by all oral cancer cell lines, such as MBTD1 and FSCN1, or downregulated in all cell lines, such as CLCN3, FLI-1, MRTFB, DAB, SRGAP1, and ABHD17C." (PMID 38396844, 2024).
cancer (5 papers, 2019 to 2023). A tumor composed of atypical neoplastic, often pleomorphic cells that invade other tissues. "MBTD1 promoted cell viability and inhibited apoptosis, and knockdown of MBTD1 reversed the cancer-promoting effects of lncRNA TTN-AS1." (PMID 31600142, 2019). "The level of MBTD1 in cancer tissues was significantly higher than that in normal tissues." (PMID 31600142, 2019).
tumour (1 paper, 2019). "Both the cell experiments and animal experiments confirmed that downregulating the level of MBTD1 reversed the effects of overexpression of lncRNA TTN-AS1 on tumour growth." (PMID 31600142, 2019). "This suggested that MBTD1 had a role in promoting tumour growth." (PMID 31600142, 2019).
MBTD1 also shares sentences with these, for which no sentence is quoted: acute myeloid leukemia (2 papers); ependymoma (1); leukemia (1); neurodegenerative disease (1); ovarian carcinoma (1); sarcoma (1); uterine disorder (1); uterine neoplasms (1).